MIR514A1 (microRNA 514a-1)
Synonyms: hsa-mir-514-1; MIR514-1; MIRN514-1; hsa-mir-514a-1; mir-514a-1
Gene: MicroRNA gene on chromosome X (147,279,247 to 147,279,344, reverse strand). Ensembl gene ENSG00000207868.
Homologues: Orthologues: chimpanzee MIR514-1 (99% identical), macaque mml-mir-514a (92% identical), chimpanzee ptr-mir-514-2 (89% identical), chimpanzee ptr-mir-514-2 (88% identical), dog MIR514 (68% identical), mouse Mir509 (62% identical), rabbit ocu-mir-506 (38% identical). Paralogues in human: MIR514A2 (89% identical), MIR514A3 (89% identical), MIR509-1 (78% identical), MIR514B (66% identical), MIR509-3 (62% identical), MIR506 (60% identical), MIR513A2 (56% identical), MIR507 (55% identical), MIR513B (51% identical).